BCAR1 (BCAR1 scaffold protein, Cas family member)
Diseases named in the same sentence as BCAR1 in open-access papers (continued):
Sharing a sentence is not in itself a finding about the gene and the disease.
cancer (continued). "Some of the most important genes with promoter DhMRs were BCAR1, which plays crucial roles in metastasis and cell adhesion, and MMP2, which functions in EMT and immune response in multiple cancer types." (PMID 33203436, 2020). "p130Cas/BCAR1 expression has been shown to be fundamental for cell transformation and tumor progression in several cancers but also in other diseases." (PMID 30390666, 2018). "The Cas scaffolding proteins (NEDD9/HEF1/CAS-L, BCAR1/p130Cas, EFSSIN, and HEPL/CASS4) regulate cell migration, division and survival, and are often deregulated in cancer." (PMID 21765937, 2011). "Therefore, a TCGA database search for growth factors involved in EGFR signaling correlated with BCAR1 expression was performed because EGFR drives proliferation and is a target for EGFR-directed antibody treatment in many carcinomas (especially CRC)." (PMID 34830244, 2021). "Interestingly, cancer genes CDH13 and BCAR1 were found with multiple KRT DhMRs, and they were also important genes for hyper-5hmC in HPV(−) tumors, which is consistent with the previous finding that the KRT subtype shares more similarities with HPV(−) HNSCC." (PMID 33203436, 2020). "The association between BCAR1 expression and lymph node metastasis was puzzling because it was in the opposite direction between the ERG negative and positive cancers and significant in both subsets." (PMID 29304771, 2018). "It is, thus, possible that post-transcriptional modifications may account for the different BCAR1 expression levels in ERG-positive and ERG-negative cancers, including for example altered protein stability." (PMID 29304771, 2018). "The minor prognostic difference between cancers with negative or strong BCAR1 expression limits its clinical impact as a stand-alone marker." (PMID 29304771, 2018). "Strong versus negative BCAR1 expression was associated with early PSA recurrence in all tumors and was limited in subgroup analyses to the subset of ERG-negative cancer." (PMID 29304771, 2018). "Here, the Ki67 labeling index (Li) ranged from 1.5% (in BCAR1 negative cancer) to 4.0% (in strongly BCAR1 positive cancer, p < 0.0001), while this association was weaker (2.2% in BCAR1 negative vs. 3.2% in BCAR1 strong, p < 0.0001) in ERG-positive cancer." (PMID 29304771, 2018). "In addition, the expression levels of CD41, CD31 (MVD), BCAR1, VEGF, LOX and FAK were positively correlated with the clinical stages in the carcinoma (SCC, MC and CCC) samples (r=0.528, 0.613, 0.575, 0.575, 0.43, 0.571 and 0.589, respectively)." (PMID 25502723, 2015). "BCAR1 overexpression confers invasiveness to cultured cells, and promotes mammary tumorigenesis and lung metastasis in the MMTV-HER2 and other mouse models of cancer." (PMID 21765937, 2011). "We targeted five cancers with sample size more than 3,000, and performed gene-set enrichment analysis in the same way; however, we did not observe significant enrichment of BCAR1 PPI subnetwork, suggesting that significant enrichment of the gene-set was not driven by specific cancers." (PMID 36737517, 2023).
tumor (73 papers, 2008 to 2025). "The expression levels of FLOT1 and BCAR1 were both significantly associated with tumor stage, depth of tumor invasion and regional lymph node." (PMID 37928269, 2023). "p130Cas, encoded by the breast cancer anti-estrogen resistance 1 (BCAR1) gene, is a scaffold protein that integrates large multi-protein complexes in response to stimuli such as hormones, growth factors, and integrin engagement." (PMID 34830244, 2021). "BCAR1, also referred to as p130 Crk-associated substrate, is located at the sites of adhesion and is associated with tumor migration, colony formation and anchorage-independent growth." (PMID 25502723, 2015). "Since loss of either Nedd9 or p130Cas/BCAR1 impairs growth of ErbB2 tumours, the full activation of crucial ErbB2 downstream effectors, such as Src and FAK, may require the co-expression of Nedd9 and p130Cas/BCAR1, suggesting that these two Cas proteins cooperate during early ErbB2 tumourigenesis." (PMID 25606587, 2014). "Previous studies have suggested that genes such as BCAR1 and PIR in tumor cells are considered oncogenic factors, with their increased expression in tumor tissues being closely associated with poor prognosis." (PMID 41430038, 2025). "Src phosphorylates the p130Cas/BCAR1 adaptor protein to induce PDPN expression in order to promote tumor cell expansion, and contact inhibition reverses this process." (PMID 35177067, 2022). "For example, the PTP1B-dependent dephosphorylation of breast cancer anti-estrogen resistance protein 1 (BCAR1) was shown to depend on the interaction of PTP1B with the SH3 domain of BCAR1." (PMID 34526379, 2021). "POLR2A was pulled down by BCAR1 in 293T cells, probably due to tissue‐specific or tumor‐specific interactions between these two proteins." (PMID 33001583, 2020). "Together, these data show that tumor relevant functions of BCAR1 and other proteins turn out to be attenuated or amplified by ERG." (PMID 29304771, 2018). "The results of this study suggest that high BCAR1 expression is a weak independent predictor of unfavorable tumor characteristics and early PSA recurrence." (PMID 29304771, 2018). "In a cohort of 151 Chinese patients with NSCLC, elevated BCAR1 protein expression levels in tumor tissues were shown to predict a poor prognosis." (PMID 28423562, 2017). "Reduction in the expression levels of BCAR1 resulted in reduced tumor growth following docetaxel chemotherapy." (PMID 25502723, 2015). "For instance, high levels of p130Cas/BCAR1 in mammary epithelial cells subvert the function of TGF-beta from a negative regulator of tumour formation to a promoter of growth and dissemination." (PMID 25606587, 2014). "Consistently, silencing of p130Cas/BCAR1 is sufficient to impair growth of MMTV-NeuT spontaneous tumours." (PMID 25606587, 2014). "Multiple studies showed that p130Cas/BCAR1 regulates multiprotein signaling pathways and cell transformation that control cell migration, adhesion, cell motility, transformation, microbial pathogenesis, survival, and tumor progression." (PMID 39036012, 2024). "CTCs, as well as tumor formation, were prohibited in nude mice xenografted with BCAR1-KO cells." (PMID 34326687, 2021). "For the cases with tumor progression, the proportion of BCAR1 positive CTCs increased." (PMID 34326687, 2021). "Therefore, a comprehensive BCAR1/EREG expression correlation analysis of the TCGA CoAd data set distinguishing tumor localization and stage was conducted." (PMID 34830244, 2021). "BCAR1 has been shown to enhance tumor proliferation, invasion, and metastasis in several cancers." (PMID 33001583, 2020).
tumor (continued). "The Gal4-dependent upregulation of PURB (transcriptional activator protein Pur-beta) and MAPKAPK3 (MAPK-Activated Protein Kinase 3) expression, as well as the downregulation of BTF3 (Basic Transcription Factor 3) and BCAR1(Breast Cancer Anti-Estrogen Resistance Protein 1), could be confirmed." (PMID 35742860, 2022). "However, BCAR1 alteration frequencies were low in TCGA data sets of 13 different tumor entities (average: 0.9%; CoAd: 1.5%), and no hotspot mutation region was found." (PMID 34830244, 2021). "Hence, BCAR1 might play a key role in the occurrence and development of tumor and could be used as a reliably metastatic biomarker." (PMID 34055638, 2021). "PTK6 can have an impact on tumor progression and metastasis through its regulation of FAK and BCAR1." (PMID 26247733, 2015). "The present study demonstrated that tumour malignancy was positively correlated with the enhanced expression of CD41, CD31 (MVD), BCAR1, FAK, LOX and VEGF using IHC." (PMID 25502723, 2015). "We have determined that PTK6 promotes tumor initiation and progression and is important for regulation of STAT3, FAK, and BCAR1." (PMID 26247733, 2015). "Intriguingly, we found that serum BCAR1 levels were significantly higher in NSCLC than in the control group, increased gradually with the progression of tumor staging, and decreased after removal of the malignant lesions." (PMID 22558353, 2012). "Recently, our study suggested that serum BCAR1 levels were significantly higher in NSCLC than in the control group, increased gradually with the progression of tumor staging, and decreased after removal of the malignant lesions." (PMID 22558353, 2012). "BCAR1 expression can result in the secretion of more exosomes with high RAC1 expression, which may alter the tumor microenvironment." (PMID 34326687, 2021). "Neither BCAR1 nor POLR2A expression was correlated with tumor size (data not shown)." (PMID 33001583, 2020). "Tumor-bearing nude mice treated with neoantigen (ACAD8-T105I, BCAR1-G23V and PLCG1-M425L)-induced NRTs exhibited significantly delayed tumor growth, whereas the irrelevant peptide-induced NRTs did not restrict tumor growth." (PMID 33928024, 2021). "However, there was no appreciable correlation between BCAR1 and other clinical-pathological characteristics including age, gender, histology, TNM stage, tumor size and lymphonode metastasis." (PMID 22558353, 2012).
infection (5 papers, 2014 to 2021). The state of being infected such as from the introduction of a foreign agent such as serum, vaccine, antigenic substance or organism. "The integrin signaling mediators BCAR1 and NEDD9, as well as MAPK3 and the SRC homology domain-containing protein SHC1, showed a strong, time-dependent phosphorylation after 90 min of infection, returning to control levels by 7 h post-infection." (PMID 25101063, 2014).
cardiovascular disease (2 papers, 2024 to 2025). "Although previous studies investigated the role of p130Cas/BCAR1 in different biologic systems, a specific comprehensive review on the cardiovascular system from the embryogenic stage to the presence of cardiovascular diseases is missing." (PMID 39036012, 2024). "However, the interaction analysis reveals that such fluxes can significantly amplify the effect size of risk variants mapped to the PLG, BCAR1 and TGFB1 risk loci, respectively, providing insights into their roles in cardiovascular disease." (PMID 40175777, 2025).
benign tumors (1 paper, 2021). "There were few CTCs detected in ten benign tumors, including 22 BCAR1 negative CTCs and 15 BCAR1 positive CTCs." (PMID 34326687, 2021).
BCAR1 also shares sentences with these, for which no sentence is quoted: melanoma (14 papers); glioma (7); hepatocellular carcinoma (6); colon cancer (5); glioblastoma (4); breast (3); type 1 diabetes (3); chronic myelogenous leukemia (2); osteopetrosis (2); osteosarcoma (2); prostate adenocarcinoma (2); rheumatoid arthritis (2); triple-negative breast carcinoma (2); alcoholic pancreatitis (1); anaplastic large cell lymphoma (1); aortic aneurysm (1); autism (1); benign skin tumors (1); cardiac hypertrophy (1); cervical cancer (1); colon adenocarcinoma (1); colorectal adenocarcinoma (1); Emery-Dreifuss muscular dystrophy (1); endometriosis (1); endothelial dysfunction (1); focal segmental glomerulosclerosis (1); hematological malignancies (1); hyperplastic (1); Hypertension (1); lymph node metastasis (1).
A further 15 diseases each share a sentence with BCAR1 in 1 paper.